IL18 (interleukin 18)
Diseases named in the same sentence as IL18 in open-access papers (continued):
Sharing a sentence is not in itself a finding about the gene and the disease.
breast cancer (continued). "Mesenchymal stem cells-expressing IL-18 inhibited the proliferation and metastasis of breast cancer cells by activating immunocytes and immune cytokines, downregulating the proliferation marker Ki-67 and suppressing tumor angiogenesis." (PMID 31492049, 2019). "Some cytokines (IL-1, IL-6, IL-11, TGFβ) stimulate, while others (IL-12, IL-18, IFNs) inhibit breast cancer proliferation and/or invasion." (PMID 31557971, 2019). "Several studies have shown that IL-18 increases PD-1 expression, leading to immunosuppression in NK cells in melanoma and breast cancer." (PMID 31731729, 2019). "• Serum IL-18 and NO activity can be used as a marker for evaluating disease activity inpatients with breast carcinoma." (PMID 31554361, 2019). "Our results revealed increased levels of both IL-18 and IL-18BP in breast cancer whereas in dense breast tissue IL-18 alone was increased." (PMID 29387062, 2017). "In this study, we investigated the role of tumor-derived IL-18 on peripheral blood NK cells in breast cancer patients." (PMID 28415798, 2017). "Further studies are now warranted to evaluate the ramifications of tumor derived IL-18 in anti-PD1/PD-L1 treatment for breast cancer." (PMID 28415798, 2017). "IL-18 added to IL-2 increases Vγ2Vδ2 T cell numbers by 2.7-fold after zoledronate stimulation of PBMC from breast cancer patients and increases the production of IFN-γ and TNF-α." (PMID 28239463, 2017). "Increased levels of IL-18 were found in dense breast tissue as well as in breast cancer, but IL-18BP was increased in breast cancer only." (PMID 29387062, 2017). "In breast cancer cell lines, IL-18 was expressed and secreted in the triple-negative breast cancer (TNBC) cell lines MDA-MB-231 and HCC-70 but not in MCF-7 cells." (PMID 28415798, 2017). "To more fully investigate the role of IL-18 in breast cancer, we examined the expression of IL-18 in various breast cancer cell lines and its effects on NK cells." (PMID 28415798, 2017). "In a similar study considering the effect of leptin on TAMs and breast cancer cells, the adipokine has been shown to induce IL-18 expression on both, eventually leading the breast cancer cells to invasion and metastasis." (PMID 28970834, 2017). "Interleukin-18-binding protein (IL18BP) regulates the activity of IL-18, which has been shown to be higher in breast carcinoma tissue compared to tissue from patients with benign breast disease." (PMID 28391240, 2017). "One study showed a link between the expression of interleukin (IL)-18, reported to have a pro-tumor effect in various cancers, and claudins in breast cancer migration." (PMID 27547510, 2016). "The results suggest that IL-18 is important for the induction of breast cancer cell migration by down-regulating claudin-12 and activating the p38 mitogen-activated protein kinase (MAPK) pathway [72•]." (PMID 27547510, 2016). "It has been proposed that MSCs expressing IL-18 inhibit proliferation of breast cancer cells by alteration of their cell cycle." (PMID 27630452, 2016). "Namely, it has been shown that human umbilical cord MSCs, previously modified for high expression of IL-18 gene, inhibit proliferation and invasiveness of breast cancer cells." (PMID 27630452, 2016). "This indicated that hUMSCs/IL-18 suppressed cancer cell proliferation by inducing the G1- to S-phase arrest of breast cancer cells." (PMID 25780408, 2015). "Higher expression levels of IL-18 are detected in different cancer types, such as gastric and breast cancer." (PMID 26376814, 2015). "On the other hand, higher IL-18 levels both in the tumor region and in the serum were detected in metastatic gastric and breast cancer." (PMID 26376814, 2015). "In the present study, hUMSCs genetically modified with IL-18 gene were used to study the effect of hUMSCs/IL-18 on the growth, migration and invasion of two breast cancer cell lines in vitro." (PMID 25780408, 2015).
breast cancer (continued). "In humans, an increase in IL-18 has been correlated with various types of cancer including ovarian carcinoma, head and neck squamous carcinoma, breast cancer, and others." (PMID 26378020, 2015). "In conclusion, the present study has demonstrated the therapeutic potential of hUMSCs/IL-18 in breast cancer treatment." (PMID 25780408, 2015). "IL-18 was further validated to contribute to doxorubicin resistance, in addition to its confirmed role in breast cancer metastasis." (PMID 21931812, 2011). "Inflammasome-related biomarkers, such as interleukin-18 (IL-18), play a role in inflammation-mediated pain, and we hypothesize that IL-18 may serve as a potential biomarker for breast cancer RT-induced pain." (PMID 41976322, 2026). "IL-18 is known to stimulate IFN-γ production and enhance NK/T cell cytotoxicity in immunological models, and elevated serum IL-18 has been associated with prognosis in breast cancer patients." (PMID 41462979, 2025). "We searched PubMed and Google Scholar to find articles published in the last 10 years or so, using keywords including NLRP3, inflammasome, immune response, IL-1β, IL-18, pyroptosis, melanoma, leukemia, breast cancer, colon cancer, lung cancer, and other cancer types." (PMID 39769450, 2024). "Therefore, ascorbate’s potential efficacy against cancer lies in its ability to diminish IL-18 expression, influencing the immune system’s capacity to counteract diverse tumor cells, including breast cancer cells." (PMID 38732186, 2024). "High levels of IL-18 are also found in breast cancer patients with metastasis." (PMID 38201482, 2023). "Importantly, Kmplot analysis reveals that high IL-18 expression is correlated with increased relapse-free survival in breast cancer patients (p = 0.00022)." (PMID 36901727, 2023). "In the current study, we convert to evaluate the differential expression and clinicopathological features of NLRP3 inflammasome pathway-related proteins, including NLRP3, caspase-1, ASC, IL-1β, and IL-18, in the tumor parenchymal and immune-stromal cells of breast cancer." (PMID 38031068, 2023). "Besides, an increased serum IL-18 level was observed in the advanced-stage of breast cancer patients as well, which was consistent with IL-1β." (PMID 36823153, 2023). "In addition, advanced-stage breast cancer patients have also been observed to have increased serum levels of IL-18." (PMID 37511974, 2023). "This is in good agreement with data showing that IL-18 may be a critical factor in breast cancer metastasis." (PMID 36286034, 2022). "The function of IL-1β and IL-18 in breast cancer are multiple." (PMID 36119049, 2022). "The possible roles of pyroptosis-related inflammasomes, gasdermins, and cytokines like interleukin-1β (IL-1β) and interleukin-18 (IL-18) in the TME of breast cancer are further elucidated to explore potential targets contributing to fight against breast cancer." (PMID 36119049, 2022). "Also, IL‐18 can be considered as a potential target for tumor treatment in YAP1 overexpressed breast carcinoma." (PMID 34196131, 2022). "Among them, IL-18 [p = 0.015, HR(95%CI): 0.832(0.717–0.965)] was a protective factor as well as GSDMC [p = 0.044, HR(95%CI): 1.120(1.003–1.251)] and TIRAP [p = 0.025, HR(95%CI): 1.336(1.037–1.722)] were risk factors for breast cancer prognoses." (PMID 34589498, 2021). "A recent preclinical study has clearly shown that inhibition of NLRP3 by miRNA is able to block tumor growth and the immune-resistance of breast cancer through ASC/IL-1/IL-18 pathways; this inhibition provides new clinical insights for the therapy of breast cancer." (PMID 34178667, 2021).
breast cancer (continued). "In a recent preclinical study, the pharmacological inhibition of NLRP3 through miRNA reduced the tumor growth and the immune-resistance in breast cancer-bearing mice through ASC/IL-1/IL-18 pathways; these data provide new clinical insights for breast cancer management." (PMID 33096896, 2020). "This suggest that ascorbate can act against breast cancer, decreasing the expression of IL-18." (PMID 33182353, 2020). "Some of these cytokines, such as IL-1, IL-6, IL-11, and transforming growth factor (TGF)-β, stimulate breast cancer proliferation and invasion, whereas other cytokines such as IL-12p70, IL-18, and IFNs exert opposite effects on breast cancer proliferation or invasion." (PMID 32703187, 2020). "The high expression of IL18 in breast cancer enables promotion of cell proliferation and migration, and could be a biomarker candidate for prognosis in breast cancer patients." (PMID 32695310, 2019). "In order to confirm the results, cells were co-incubated with IL-18 siRNA or IL-18BP-Fc chimeras and the effect of TAMs to promote migration and proliferation of breast cancer cells when stimulated by leptin was abrogated, thus proving the link between the process." (PMID 28970834, 2017). "Another study suggests that IL-18 enhances breast cancer cell migration." (PMID 28391240, 2017). "Whether this is an advantage or disadvantage regarding breast cancer progression remains to be elucidated when the exact biologic role of IL-18 in cancer development is determined." (PMID 29387062, 2017). "This study showed that exogenous IL-18 could enhance breast cancer cell migration and inhibit the expression of claudin-1, 3, 4, and 12 in human breast cancer cell line MCF-7." (PMID 27547510, 2016). "In conclusion, hUMSCs/IL-18 can suppress the proliferation, migration and invasion of breast cancer cells in vitro and may provide an approach for a novel antitumor therapy in breast cancer." (PMID 25780408, 2015). "Given the theoretical immunostimulatory aspect of IL-18 function, the paradox of finding increased circulating IL-18 as a negative prognostic portent has been discussed without resolution in the context of both pancreatic cancer and breast cancer." (PMID 25963312, 2015). "The mechanism of this proliferation suppression may have involved the induction of G1- to S-phase arrest of the breast cancer cells by the hUMSCs/IL-18." (PMID 25780408, 2015). "It was demonstrated that genetically engineering hUMSCs to produce IL-18 had synergistic therapeutic benefits and that such cells could contribute to an adoptive immunotherapy for breast cancer and thereby provide a promising new treatment option." (PMID 25780408, 2015). "Considering the confirmed roles of IL-18 in breast cancer progression and metastasis, our work revealed for the first time to our knowledge that IL-18 might play dual functions in drug resistance and tumor metastasis." (PMID 21931812, 2011). "Due to its dual roles in both drug resistance and tumor metastasis, IL-18 may represent a useful drug target for breast cancer therapy." (PMID 21931812, 2011). "Therefore, our data support that YAP1 was increased in breast cancer, which might mainly originate from its increased DNA copy number and almost unchanged IL‐18." (PMID 34196131, 2022). "Thus, ascorbate may be efficacious against cancer by decreasing the expression of IL-18, which is able to regulate the escape of different tumor cells, including breast cancer cells, from the immune system." (PMID 33182353, 2020). "Indeed IL-18 expression leads to invasion and metastasis of breast cancer cells through PI3K-AKT/ ATF-2 signaling, and it might be regulated through NF-κB/NF-κB1 signaling in TAMs43." (PMID 32695310, 2019). "In the present study, a novel possibility that IL-18 could have a function in the treatment of breast cancer was revealed; however, further experiments are necessary to verify the effect of hUMSCs/IL-18 on breast cancer in vivo." (PMID 25780408, 2015).
breast cancer (continued). "Similarly, there were no significant changes in the cardiac transcript levels of the inflammatory markers interleukin 1β, interleukin 18, monocyte chemoattractant protein-1, Galectin-3 (Mac-2), or the number of Galectin-3 (Mac-2)–positive cells in all groups of our mouse model of breast cancer." (PMID 37969640, 2023). "A nomogram was constructed using 7 IRGs, including GPR132, IFITM1, IL12B, IL18, IRF7, KCNMB2, and TACR1, to predict the 1-, 2-, and 3-year survival of breast cancer patients." (PMID 37304237, 2023). "Regarding unique markers, CA15-3 and TNF-alpha were two of several breast cancer-specific, and CA19 and IL-18 were pancreatic cancer-specific." (PMID 37181043, 2023). "Therefore, SAA and IL-18 may be prognostic markers for breast cancer recurrence." (PMID 38169859, 2023). "Like IL-1β, IL-18 has both pro and antitumorigenic effects by regulating the TME in breast cancer as well." (PMID 36823153, 2023). "IL-18, a member of the IL-1 family of cytokines, increases the migration of MDA-MB-468, MDA-MB-231, and BT-549 human breast cancer cells through the p38 MAPK signaling pathway." (PMID 35954317, 2022). "Then, both univariate and multivariate logistic regression analyses demonstrated that 6 genes regulated by the RUNX family had a significant relationship with the prognosis of breast cancer patients, including PSME2, ULBP2, IL18, TSLP, NPR3, and TRDV1." (PMID 36092942, 2022). "PSME2, IL18 and NPR3 have been reported to have a close correlation with the proliferation, invasion, and migration of various tumors including breast cancer." (PMID 36092942, 2022). "Whereas in primary breast cancer, the genetic alteration of IFNG is significantly low and IL‐18 and YAP1 showed almost same level of gene alteration." (PMID 34196131, 2022). "Compared with a human mammary epithelial cell line MCF-10A, the expression levels of GSDMC, GZMB and IL18 were upregulated, while TP63 was found with lower expression level in breast cancer cells SK-BR-3, BT-549, MCF-7, and MDA-MB-231 using RT-qPCR assay." (PMID 36936274, 2022). "As shown, compared with MCF-10A, the expression levels of GSDMC, GZMB and IL18 were upregulated, while TP63 was found with lower expression level in breast cancer cells SK-BR-3, BT-549, MCF-7, and MDA-MB-231 (P < 0.05)." (PMID 36936274, 2022). "As depicted in western blotting, IL-18, GSDMC, and TIRAP expression was all markedly up-regulated in breast cancer cells MDA-MB-231 and HCC70 compared with normal breast cells MCF-10A." (PMID 34589498, 2021). "Leptin-induced IL-18 expression was regulated via NF-κB/NF-κB1 signaling in TAMs and via PI3K-AKT/ATF-2 signaling in breast cancer cells, which eventually leads to invasion and metastasis in the latter." (PMID 34912237, 2021). "Moderate exercise can reduce the expression of mRNA levels of TNF-α, IL-6, IL-18, and CRP in the livers of breast cancer mice." (PMID 32309219, 2020). "Thus, IL-18 could drive breast cancer progression by inducing PD-1-dependent immunosuppression." (PMID 31492049, 2019). "Conversely, lung cancer, melanoma, breast cancer and HNSCC, demonstrated that NLRP3 inflammasomes, IL-1β and IL-18 promote tumor growth, proliferation, invasion and metastasis." (PMID 30447690, 2018). "Some cytokines and growth factors (IL-1, IL-6, IL-11, TGF-β, and VEGF) stimulate the proliferation and invasion of breast cancer cells, whereas others (IL-12, IL-18, and IFN) suppress breast cancer progression." (PMID 27484639, 2016). "There were significant baseline differences between lymphoma versus breast cancer patients for TNF-α, TNFR1, TNFR2 and IL-18." (PMID 25909710, 2015).
breast cancer (continued). "In the study by Qiao and others, there is an interaction between menopause and BMI and IL-18 (IL-1 family member)–607 G/T genotype in the group of breast cancer patients with LN metastases and the non-metastasis group." (PMID 40584290, 2025). "We selected IL18, which has never been reported in breast cancer before, in the signature to learn more about its function, potential to predict outcome, and immune system role." (PMID 38771140, 2024). "To confirm that the antitumor immunity in the 4T1 breast cancer mouse model was induced by GSDMBNT mRNA@LNP-mediated pyroptosis, we investigated the expression of ICD biomarkers (CRT and HMGB1) and pyroptosis-related cytokines (IL-1β and IL-18)." (PMID 37454146, 2023). "The innovative discovery of the study, which differs from previous research, is that elevated IL-18 expression in breast cancer stromal cells, rather than tumor cells, correlates with an unfavorable prognosis." (PMID 38031068, 2023). "They discovered that IL‐18 induces cell migration via down‐regulation of claudin‐12 and activation of the p38 MAPK in vitro; hence, it can be crucial in metastasis and pathogenesis in breast cancer." (PMID 34196131, 2022). "Therefore, we aimed to investigate the effects of exercise on inflammatory cytokines interleukin (IL)-6, IL-18, tumor necrosis factor-α (TNF-α), and C-reactive protein (CRP) in a breast cancer mouse model." (PMID 32309219, 2020). "There might be a reduced inflammatory process via a reduction in TNF-α, IL-6, IL-18, and CRP expression in breast cancer mice that were subjected to moderate intensity exercise." (PMID 32309219, 2020). "Previously, the role of tumor derived IL-18 has not been investigated in terms of the effects on breast cancer and NK cells." (PMID 28415798, 2017). "The specific and non-specific anti-tumor effects were confirmed in IL-18 gene transfected dendritic cells and breast cancer cells." (PMID 24066061, 2013). "Additionally, DOX-induced breast cancer cell-conditioned medium (D-CM) exhibits similar toxic effects as D-BCC-EXOs, as evidenced by comparable reductions in cell viability and increases in LDH, IL-1β, and IL-18 levels." (PMID 40360476, 2025). "The increase in Il-18 expression seen at both the level of mRNA and protein in tumors treated with MSU-42011, but not bexarotene, suggests that this RXR agonist promotes a pro-inflammatory tumor microenvironment, which can be harnessed for breast cancer treatment." (PMID 36901727, 2023). "The tumor-promoting effects of IL-18 were also shown by IL-18 induction of PD-1 expression on NK cells in the TME, leading to a poor prognosis in nasopharyngeal carcinoma, and high expression of IL-18 in TAM promoted the migration and invasion of breast cancer cells." (PMID 35739593, 2022). "According to a recent study, Leptin could induce IL-18 expression in both TAMs controlled by NF-B/NF-B1 and breast cancer cells controlled by PI3K-AKT/ATF-2 signaling, which, eventually, leads to the invasion and metastasis of breast cancer cells." (PMID 36119049, 2022). "Thus, among the pro-inflammatory cytokines in breast cancer, the content of IL-1β, IL-2, and IL-6 increased (+16.1%, +25.0%, and +12.7%, respectively), while for TNF-α, MCP-1, IL-8, and IL-18, the content decreased (−36.2%, −23.8%, −15.0%, and −12.1%, respectively)." (PMID 36286034, 2022). "Thus, based on our analysis, we hypothesized that IL‐18 either acts as a regulatory factor in the expression of YAP1 or interacts with it to determine the occurrence and progression in breast carcinoma." (PMID 34196131, 2022).
breast cancer (continued). "This study aimed to investigate cytokine mRNA expression levels of IL-6, IL-18, TNF-α, and CRP in hepatocytes from breast cancer xenograft mice with or without moderate exercise." (PMID 32309219, 2020).